PALB2 (partner and localizer of BRCA2)
Diseases named in the same sentence as PALB2 in open-access papers (continued):
Sharing a sentence is not in itself a finding about the gene and the disease.
breast cancer (continued). "While the degree of breast cancer susceptibility is still unclear, some studies examining recurrent PALB2 mutations tested in patients unselected for family history have demonstrated a risk and penetrance as high as those arising from BRCA2 mutations." (PMID 25225577, 2014). "Mutations in PALB2 have been identified in almost all breast cancer populations studied to date, but the rarity of these mutations and lack of information regarding their penetrance makes genetic counseling for these families challenging." (PMID 25225577, 2014). "Pancreatic and breast cancers have been previously associated with a PALB2 mutation but this study was the first instance of it occurring in an individual with both cancer types." (PMID 24949998, 2014). "Previously, we reported the use of ROVER in the context of screening for genetic mutations in the breast cancer predisposition gene, PALB2 [GenBank reference sequence NM_024675; MIM#610355]." (PMID 24461215, 2014). "Similar to BRCA2, germline mutations in PALB2 have been shown to predispose to Fanconi anaemia as well as pancreatic and breast cancer." (PMID 24949998, 2014). "Similar to mutations in BRCA1 and BRCA2, the risks associated with monoallelic mutations in PALB2 seem to extend beyond breast cancer." (PMID 25225577, 2014). "Our data, together with that of many others have shown that the prevalence of PALB2 mutations in the context of multiple-case breast cancer families is potentially relevant to their clinical management." (PMID 23448497, 2013). "The tumour pathology of breast cancers arising in women who carry germline nonsense or frameshift mutations in PALB2 was examined." (PMID 23448497, 2013). "We sought to ascertain the prevalence of PALB2 mutations in these women due to the high estimated breast cancer risk associated with at least some PALB2 mutations and to further consider if clinical testing for these mutations is warranted." (PMID 23448497, 2013). "The youngest affected woman, not known to carry a mutation in BRCA1 or BRCA2, from 747 multiple-case breast cancer families participating in kConFab were selected for PALB2 mutation screening." (PMID 23448497, 2013). "Like BRCA2, PALB2 itself is also mutated in breast cancer, pancreatic cancer, ovarian cancer and Fanconi anemia (FA)." (PMID 23585894, 2013). "Within the familial context, germline PALB2 mutations are associated with a 2.3 to 6 fold increased risk to breast cancer." (PMID 23977390, 2013). "Heterozygous germline loss-of-function mutations in PALB2 are associated with increased risk of breast cancer." (PMID 23448497, 2013). "Cao et al64 found that the frequency of disease-related germline mutations in PALB2 was 0.8% (3/360) in BRCA1/BRCA2-negative Chinese women with early-onset or familial breast cancer." (PMID 23318652, 2013). "In summary, we found 2 germline PALB2 deleterious mutation carriers in 122 high risk non-BRCA1 or BRCA2 breast cancer patients by DNA sequencing and 1 germline carrier in 1406 breast cancer patients by genotyping." (PMID 23977390, 2013). "Mutations in PALB2 gene were originally associated with a moderate (2–3 fold) increase risk for breast cancer." (PMID 23935836, 2013). "Although rare, PALB2 mutations have been shown to confer high risks for the development of breast cancer." (PMID 23448497, 2013). "We report the identification of two nonsense and two frameshift mutations of PALB2 in 1.5% of familial breast cancer cases recruited from Familial Cancer Clinics in Australia and New Zealand." (PMID 23448497, 2013). "High throughput screening of the PALB2 coding and flanking intronic regions in 747 affected women from multiple-case breast cancer families identified 26 different PALB2 genetic variants." (PMID 23448497, 2013).
breast cancer (continued). "A study involving individuals in the UK population found the minor allele frequency of PALB2 c.2993G>A to be 33/1846 (1.8%) for familial breast cancer cases and 44/2168 (2.0%) for unaffected controls." (PMID 23448497, 2013). "We evaluated the contribution of PALB2 germline mutations in 122 Asian women with breast cancer, all of whom had significant family history of breast and other cancers." (PMID 23977390, 2013). "Similar carrier frequencies of this PALB2 variant in breast cancer cases and unaffected controls were also observed in the Finnish population." (PMID 23448497, 2013). "As in other Fanconi anemia genes, monoallelic mutations in PALB2 have been associated with increased breast cancer risk." (PMID 23935836, 2013). "Penetrance estimation for conferring breast cancer risk has been hampered by the paucity of cases, although estimates of 2- to 6-fold increased risk to breast cancer have been suggested, thus classifying PALB2 as a moderate breast cancer risk allele." (PMID 23302520, 2013). "Given the prevalence, breast cancer risk, and tumour grade associated with this mutation, consideration of clinical PALB2 testing is warranted." (PMID 23448497, 2013). "Mutations in PALB2 were also detected in European families and, interestingly, each of these had also a history of breast cancer." (PMID 23586058, 2013). "Of these, 6 were tested in a case-control analysis and our results suggest that 5 are likely to be either benign (PALB2 Q559R, I309V, D498Y, P249L and E352Q) or associated with a low increased risk of breast cancer." (PMID 23977390, 2013). "It has recently become clear that the PALB2 gene should not only be considered as a susceptibility gene for breast cancer but also for pancreatic cancer." (PMID 23935836, 2013). "Further work is warranted to examine the pathology of breast cancers arising in PALB2 mutation carriers." (PMID 23448497, 2013). "PALB2 mutations seem to explain only a small fraction of the clustering of both pancreatic and breast cancer." (PMID 23935836, 2013). "In recent years it has become evident world-wide that also women carrying a heterozygous germline mutation in PALB2 are at significantly increased risk of getting breast cancer." (PMID 23941127, 2013). "The PALB2 c.2323C>T [p.Q775X] mutation has been reported in at least three breast cancer families and breast cancer cases of French Canadian descent and this has been attributed to common ancestors." (PMID 23302520, 2013). "Altogether, PALB2 emerges as a third important breast cancer susceptibility gene with moderate- to high penetrance mutations for breast cancer." (PMID 24025454, 2013). "Truncating mutations in the PALB2 gene are rare but are thought to be associated with increased risks of developing breast cancer in various populations." (PMID 23977390, 2013). "Mutations in PALB2 gene were originally associated with an increased risk for breast cancer and later, with pancreatic cancer." (PMID 23935836, 2013). "It has been shown that some PALB2-associated breast cancers display a more aggressive tumor phenotype, including triple-negative disease, higher tumor grade and higher Ki67 expression." (PMID 23935836, 2013). "Mutations in PALB2 predispose to breast cancer and gastric cancer, and the penetrance for breast cancer in Finnish multiple-case families has been found similarly high as for BRCA2 mutations." (PMID 24025454, 2013). "Another founder mutation in PALB2 is recurrent in British and Australian breast cancer patients, including multiple-case families." (PMID 24025454, 2013). "Further screening for nine PALB2 mutations was conducted in 874 Malaysian and 532 Singaporean breast cancer patients, and in 1342 unaffected Malaysian and 541 unaffected Singaporean women." (PMID 23977390, 2013).
breast cancer (continued). "The carrier had bilateral breast cancer at ages 34 and 42 years and a strong family history of breast cancer further supporting the notion that PALB2 p.Q775X carriers are at increased risk for breast cancer." (PMID 23302520, 2013). "Germline mutations in PALB2 have been identified in approximately 1% of familial breast cancer and 3–4% of familial pancreatic cancer." (PMID 23935836, 2013). "PALB2 mutations have also been linked to pancreatic cancer in families with concomitant breast cancer." (PMID 23941127, 2013). "In summary, we found that PALB2 mutations occur with a prevalence of 1.5% in a population of BRCA1/2-negative breast cancer patients specifically selected from a personal and/or familiar history of pancreatic cancer." (PMID 23935836, 2013). "Familial pancreatic and/or breast cancer due to PALB2 mutations is inherited in an autosomal dominant pattern, while Fanconi anaemia is an autosomal recessive condition." (PMID 23586058, 2013). "We recently, estimated a PALB2 mutation prevalence of 0.75% for Spanish breast/ovarian cancer families with at least one male breast cancer case." (PMID 23935836, 2013). "In another study, rare germline mutations in PALB2 were identified among patients with breast cancer." (PMID 23586058, 2013). "Subsequent studies reinforced this connection showing that truncating mono-allelic mutations in BRIP1/FANCJ and PALB2/FANCN had a frequency of approximately 1% in familial breast cancer cases." (PMID 22383991, 2012). "We estimated from analyses of case carrier families that carriers of the PALB2 c.3113G > A mutation who are relatives of unselected case carriers have a high risk of developing breast cancer: about 50% to age 50 years and 90% to age 70 years." (PMID 21182766, 2010). "HRM screening for PALB2 mutations for 779 families with multiple cases of breast cancer recruited through Australian and New Zealand clinics by the kConFab consortium identified a further eight (1.0%) families that carried the PALB2 c.3113G > A mutation." (PMID 21182766, 2010). "Studies conducted in the United Kingdom, Finland, Italy, Spain and Canada have shown that, while rare, mutations in PALB2 are far more common in breast cancer patients with a strong family history than in unaffected population-based controls." (PMID 21182766, 2010). "Two of the 695 probands diagnosed before the age of 40 years were found to carry the PALB2 c.3113G > A (W1038X) mutation, and both had strong family histories of breast cancer." (PMID 21182766, 2010). "This is in agreement with previous reports, in which alterations of the PALB2 gene were predominantly associated with familial breast cancer." (PMID 20122277, 2010). "Some of PALB2 gene alterations in breast cancer were suggested to be founder mutations for other ethnic groups." (PMID 20122277, 2010). "This method estimated that, on average, PALB2 protein-truncating mutations conferred a 2.3-fold increased risk of breast cancer (95% CI, 1.4-3.9; P = 0.0025)." (PMID 21182766, 2010). "Some authors reported PALB2 mutations also in pancreatic cancer, male breast cancer and in a single prostate cancer family." (PMID 20122277, 2010). "We demonstrate a novel inherited monoallelic deletion of the PALB2 gene in ovarian and breast cancer patients which seems to be a recurrent mutation for the population of central Poland." (PMID 20122277, 2010). "We tested Australian women affected and unaffected by breast cancer and selected and unselected for family history for PALB2 mutations to estimate the prevalence and penetrance of these mutations in the Australian population." (PMID 21182766, 2010). "As a group, women who carry germline mutations in partner and localizer of breast cancer 2 susceptibility protein (PALB2) are at increased risk of breast cancer." (PMID 21182766, 2010). "The PALB2 c.3113G > A mutation appears to be associated with substantial risks of breast cancer that are of clinical relevance." (PMID 21182766, 2010).
breast cancer (continued). "The low frequency of PALB2 mutations (0.6%) observed in our study is similar to that noticed for breast cancer by other authors." (PMID 20122277, 2010). "To characterize breast carcinomas with the PALB2 mutation more specifically, we evaluated the expression of CK5/6, CK14, CK17, EGFR and CD117." (PMID 20122277, 2010). "In the Finnish study by Erkko and colleagues a novel PALB2 founder mutation (c.1592delT) was identified among Finnish breast cancer families (OR 11.3, CI 1.8-57.8) increasing the risk to breast cancer 4-fold." (PMID 20003494, 2009). "PALB2 1592delT mutation is associated with increased breast cancer and suggestive prostate cancer (PRCA) risk in Finland." (PMID 20003494, 2009). "PALB2 was recently identified as a breast cancer susceptibility gene and mutations in it have since been reported in other populations." (PMID 18501021, 2008). "Recent studies have reported several mutations in PALB2 to be associated with an increased risk of breast cancer." (PMID 18637200, 2008). "At least in the Finnish population the major breast cancer associated aberration in PALB2 appears to be the previously reported founder truncation mutation." (PMID 18501021, 2008). "The breast cancer associated mutations identified in PALB2 are expected to be deleterious, and all result in protein truncations." (PMID 18501021, 2008). "We sought to estimate the contribution of PALB2 mutations to the burden of breast cancer in French Canadians from Quebec." (PMID 18053174, 2007). "We have identified the PALB2 mutation Q775X to be a founder mutation for breast cancer in the French-Canadian population." (PMID 18053174, 2007). "PALB2 can be added to the list of breast cancer susceptibility genes for which founder mutations have been identified in the French Canadian population." (PMID 18053174, 2007). "Although mutations are infrequent, PALB2 can be added to the list of breast cancer susceptibility genes for which founder mutations have been identified in the French-Canadian population." (PMID 18053174, 2007). "Disease-associated variants in PALB2 are rare in the UK population, with only approximately 1% of familial breast cancer being attributable to mutations in this gene, whereas 1% of all breast cancer in Finland is due to a single mutation (1592delT) in PALB2." (PMID 18053174, 2007). "Studies including clinical samples from the UK, The Netherlands, Finland, and Canada have confirmed that, like BRCA2, PALB2 is both a breast cancer susceptibility gene and a Fanconi anemia gene." (PMID 18053174, 2007). "Talazoparib demonstrated benefit in germline PALB2‐mutated advanced breast cancer." (PMID 41510186, 2026). "There was evidence of reduced breast cancer risk with breastfeeding in PALB2 PV carriers, which may offer a practical option for risk modification." (PMID 40298171, 2025). "The wider adoption of multigene panel testing resulted in identifying other variants, some like PALB2 are associated with an increased risk of breast cancer and may influence decisions regarding risk-reducing strategies and surveillance." (PMID 41568010, 2025).
breast cancer (continued). "In addition to enabling enhanced surveillance and access to preventive strategies, early awareness of a germline pathogenic variant in BRCA1/2 or PALB2 vastly influences surgical decision making when a patient is diagnosed with breast cancer." (PMID 40275390, 2025). "ATM and PALB2 are two of the main breast cancer susceptibility genes." (PMID 39518003, 2024). "Furthermore, carriers of PALB2 mutation have a 35% cumulative risk of developing breast cancer at the age of 70 years, and ATM with PVs has been detected in 1.2%–6.9% of all breast cancer cases." (PMID 39590127, 2024). "A recent large multinational study demonstrated that monoallelic pathogenic PALB2 germline variants predispose to female and male breast cancers with relative risks above 7, and by the age of 80 years 53% (CI 95%: 44–63%) of the female mutation carriers are predicted to develop the malignancy." (PMID 38597967, 2024). "Similar to BRCA mutations, PALB2-associated breast cancers may exhibit sensitivity to PARP inhibitors." (PMID 38674216, 2024). "The primary objective of this study was to determine the prevalence of GPVs in BRCA1, BRCA2, and PALB2 (B1B2P2) as well as in other breast cancer susceptibility genes (BCSGs) within a racially and ethnically diverse cohort of women with newly diagnosed breast cancer." (PMID 39226054, 2024). "This analysis revealed that some individuals with a pathogenic variant in PALB2 were diagnosed with breast cancer well before the age of 50 and had a similar risk to those with a BRCA2 variant before the age of 50 when, until recently, guidelines recommended beginning screening for everyone." (PMID 39669587, 2024). "The tumors arising from PALB2 mutations are typically luminal ones, but also the proportion of triple-negative breast cancers is higher among PALB2 mutation carriers than in women with sporadic breast cancer." (PMID 38597967, 2024). "However, numerous studies on PALB2 germline pathogenic variants in early-onset breast cancer have been focused on Europeans and Americans, with limited data available on young Chinese patients." (PMID 38914840, 2024). "Additionally, we observed an approximately 2-fold occurrence of PALB2 pathogenic variants in breast cancer patients aged ≤ 30 years compared to those aged 31-40 years (1.3% vs 0.68%), however, the difference was not statistically significant (p = 0.398)." (PMID 38914840, 2024). "Moreover, patients with HR+/HER2- breast cancer exhibited the highest frequency of PALB2 pathogenic variants (1.08%) compared to other subtypes, with only 0.41% identified in TNBC." (PMID 38914840, 2024). "Nonetheless, a study of the remaining lifetime risk for the subset of women who were older than 65 years in the population-based CARRIERS project indicated that BRCA1, BRCA2, and PALB2 PVs were associated with enough breast cancer risk to warrant high-risk screening." (PMID 37861889, 2024). "PALB2 protein participates in a process of the homologous recombination, and there is evidence that rapid and durable responses could be achieved with a platinum-based chemotherapy in PALB2-associated breast cancers." (PMID 38817905, 2024). "PALB2 carriers had the greatest increase in P/LP variant detection rates through expanded testing, starting at 21% for current practice, 34% for optimised referral, and 80% for testing all breast cancers." (PMID 39766065, 2024). "However, the frequency of PALB2 pathogenic variants in TNBC was 1.9% in the unselected breast cancer cohort." (PMID 38914840, 2024). "Female BRCA1/2 and PALB2 germline pathogenic variant carriers have an increased lifetime risk of breast cancer and may wish to consider risk-reducing mastectomy (RRM) for surgical prevention." (PMID 38248108, 2024).